RELA (RELA proto-oncogene, NF-kB subunit)
Diseases named in the same sentence as RELA in open-access papers (continued):
Sharing a sentence is not in itself a finding about the gene and the disease.
infection (continued). "In our study, we found that infection of H.pylori activated NF-κB with the overexpression of MyD88, p65/RelA and p50/NF-κB1 in AGS cells." (PMID 23437218, 2013). "Treatment with the PDE4i also lead to reduced expression of the transcriptional regulator relA, which is essential for Mtb survival under stress conditions, as well as for infection, persistence and dissemination in mice and guinea pigs." (PMID 21949656, 2011). "Uncoupling RelA degradation from γHV68 infection restored NFκB-dependent cytokine gene expression and elevated cytokine production." (PMID 22110409, 2011). "Evidently, γHV68 infection effectively uncouples NFκB activation from IKKβ activation by inducing RelA degradation in an IκBα-independent manner." (PMID 22110409, 2011). "Initial localization studies indicate that mCMV infection changed the cell-specific expression of FN, NF-κB2, RelA, RelB, and Shh and Smad7 proteins." (PMID 18371224, 2008). "Our own mathematical studies identified that RelA NF-κB may promote CHPV yield by limiting infection-inflicted cell death." (PMID 40964367, 2025). "Following Ad5-GFP infection, this analysis confirmed the decreasing and increasing GR enrichment patterns in the previously identified 8,221 GBRs, and these profiles again revealed low and high levels, respectively, of RELA recruitment." (PMID 41488369, 2025). "Together, these results indicate that KSHV de novo infection induces RelA deamidation." (PMID 38365882, 2024). "In our study, RELA was downregulated only 7 days post-infection." (PMID 38467747, 2024). "Polymorphic variants found in the warthog RelA gene have been suggested as a potential genetic factor to explain the surviving phenotype upon infection with ASFV, but this was never firmly established." (PMID 38658979, 2024). "Notably, our transposon mutant study further confirmed that singly-gene disruption of relA, spoT or dksA significantly decreased the growth of interacting A. baumannii during early macrophage infection." (PMID 35231068, 2022). "Previous studies in a fish model of infection with A. hydrophila demonstrated the expression of RELA gene and the NF-κB pathway that could result in the production of several cytokines such as TNF-α, IL-1β, IL-12, IL-8, IL-6, and IFN." (PMID 35874671, 2022). "Early studies linked RelA-dependent (p)ppGpp production with optimal expression of CT, TCP, and two major virulence regulators (ToxR and ToxT), and with virulence in rabbit ileal loop and suckling mouse infection models." (PMID 33343543, 2020). "Since environmental factors could play a role in the stimulation of ppGpp production, we investigated the expression of relA and spoT using a bioluminescent reporter fusion to track the infection progress in vivo." (PMID 29021784, 2017). "Indeed, the γ134.5 mutant sequentially induced phosphorylation of IRF3 and RelA/p65 at 3 h post infection of DCs." (PMID 28150813, 2017). "After infection, nuclear localization of P50, p52, RelA, and RelB was detected." (PMID 28346502, 2017). "Notably, transient application of Cm at 0, 24, and 48 hpi resulted in even higher levels of phosphorylated RelA at 24, 48, and 72 hpi, respectively, suggesting that C. burnetii proteins dampen NF-κB activation during infection." (PMID 28066723, 2016). "However, when compared to 24 hpi, RelA phosphorylation levels significantly increase at 48 hpi (early to mid-infection) and remain elevated through 96 hpi (mid infection)." (PMID 28066723, 2016). "Indeed, γHV68 potently activated IKKβ within 15 to 30 minutes post-infection, which correlated with the Ser468 phosphorylation of RelA." (PMID 22110409, 2011).
infection (continued). "In contrast, infection of p65/RelA-deficient MEFs with reovirus did not lead to tBid generation even though efficient viral replication is observed in these cells." (PMID 20617182, 2010). "This links with the observation that the relA gene was over-expressed in M. tuberculosis extracted from DCs compared to Mφs at 18 h post-infection indicating that the stringent response may be regulated in a cell-specific manner." (PMID 18167562, 2008). "Surprisingly, little attention has been directed in these studies toward the possibility that loss of ability to survive in vivo in absence of relA might be attributable to development of an immune response that facilitates clearance of infection." (PMID 34696193, 2021). "Thus, the reduction in RelA RNA expression detected in poly (I:C) treated cervical tissues on day 5 after infection may have also contributed to reduce HIV-1 transcription." (PMID 26121689, 2015). "The induction of IRF1 by RelA may be a primitive and pivotal event in response to infection." (PMID 26460486, 2015). "Thus, hrHPV upregulates the expression of IFRD1 soon after infection, thereby effectively decreasing the basal levels of transcriptionally active RelA and as a consequence the levels of pro-inflammatory cytokines induced via various innate and adaptive immune-mediated NFκB stimulatory pathways." (PMID 26055519, 2015). "The expression of RELA in virtually all cell populations suggests that it is a fundamental and broadly regulated factor that may maintain essential functions and responsiveness in the physiological state of the cell, especially in response to inflammation, infection, or cellular damage." (PMID 40435035, 2025). "For instance, L. amazonensis interferes with NF-κB TF function through downregulation of RELA, NFKB1, and NFKB2 during early infection in BMDM." (PMID 39639867, 2024). "The list of transcription factors modulated by the infection includes the IRF, MYC-MAX, NFY, and E2F families; RELA; YY1; CREB1; and others." (PMID 37998351, 2023). "The protein levels of NF-κB/RelA and IRF3 are stable within 24 h infection, while the level of IRF7 is increased at 12 h p.i." (PMID 37423306, 2023). "The motifs discovered were then compared with known TF binding motifs, revealing enrichment at loci opening chromatin during infection for the AP-1 (JUN-FOS), RELA (an NFκB family member) and RREB1 TFs." (PMID 36178892, 2022). "We found that the RelA/p65 and p-Ser536 RelA/p65 bound to the HCMV MIEP within 1 h of Towne strain infection." (PMID 35269913, 2022). "After 2 h of infection, the transcriptional upstream regulators EGFR, EGR1, FOXL2, FOXO3, IL1A, IL1B and RELA were activated in MKN-28 cells infected with either H. pylori wt or the ΔhtrA mutant, while WWTR1 was inhibited." (PMID 37193047, 2022). "While the fitness advantage of the relA mutation was not present in planktonic culture, we determined that it was significant in the biofilm elimination model, whereby the mutant survived exposure to several antibiotics used to treat infection, suggesting an increase in antibiotic tolerance." (PMID 28049149, 2017). "Poliovirus, HRV14, echovirus type 1, and FMDV cleave p65/RelA during infection and the EV71 2C protein has also been shown to inhibit NFκB by binding to p65/RelA." (PMID 27999393, 2016). "Total tissue RNA was isolated before and on days 1 and 3 after infection, and evaluated for IRF7, IFNα, HIV-1 and RelA transcription." (PMID 26121689, 2015). "The results showed even more clearly that RelA was cytoplasmic in PBS-inoculated bladders and that it became nuclear upon UTI89 infection in cells with surface-attached E. coli." (PMID 26549759, 2015).
infection (continued). "Enhanced anti-viral responses and IRF7 down-regulation of RelA expression likely results in decreased HIV-1 replication and improved TFV’s efficacy specifically early during infection and in the presence of suboptimal TFV concentrations." (PMID 26121689, 2015). "Upon infection of primary bone marrow-derived macrophages (BMDMs), MCMV inhibited nuclear translocation of NF-κB p65 (RelA) after stimulation of TLR7 or TLR9." (PMID 22319449, 2012). "Collectively, these findings allow us to propose a model in which, early in infection, low levels of individual enhanceosome components cooperate to tether CBP/p300 to the ifnβ locus in a manner crucially dependent on NF-κB RelA." (PMID 22022260, 2011). "Seven differentially expressed genes (DDX58, STAT1, MX1, IRAK1, MAPK11, RELA, and ICAM1) were randomly selected and quantified using qRT-PCR to validate the differential expression observed in A549 cells using RNA-Seq across varying infection time points." (PMID 38673764, 2024). "Here, infection with RNA viruses, such as Sendai virus or vesicular stomatitis virus, resulted in the upregulation of an ERV-derived lncRNA, which facilitated the expression of the NF-κB subunit RELA." (PMID 35891571, 2022). "RelA translocation was observed in macrophages infected with M. tuberculosis CDC1551 and in macrophage infected with the complemented strain after 18 hours of infection." (PMID 34276695, 2021). "We interpreted the different results between the EOP and growth assays to indicate that these genes (trpA, phoR, isdB, sodM, fmtC, and relA)mostly influence survival postinfection and do not necessarily prevent infection." (PMID 33441407, 2021). "In this respect, interaction of glycoprotein D with HVEM was reported to induce TRAF- and RelA-mediated upregulation of pro-survival genes, which might be diminished in HVEM-KO cells upon T-VEC infection." (PMID 34205379, 2021). "The female mice exhibited higher expression levels of AKT1, BTK, CCL9, and LSP1 (KO, 1A0), PPARG (KO, 1A0, and 6A2), CFLAR, and ERP44 (1A0, 6A4), CCL9 (KO, 1A0, and 6A4), RCC2, and RELA (KO), KAT2B (6A2) and FKBP5 (1A0, 6A2, and 6A4) compared to males in response to infection." (PMID 32670284, 2020). "It is worth to mention that the production and/or release of p50 from the cytoplasm and translocation of an active NF-κB dimer (not including RelA) was observed under infection by the laboratory strain CVS." (PMID 29084252, 2017). "RelA levels at each time post-infection were consistent throughout infection, indicating C. burnetii does not modulate the relative expression of RelA." (PMID 28066723, 2016). "The NFκB complex consists of 5 proteins [NFκB1 (p105), NFκB2 (p100), RELA (p65), RELB and REL (c-Rel)] and, upon activation, provides a powerful defense mechanism against infection and stress; regulation of the complex in managed in part by families of NFκB inhibitor genes (IκB) and kinases (IKK)." (PMID 27078000, 2016). "In contrast, infection with the S. Typhimurium ΔgogA ΔgtgA ΔpipA mutant strain did not alter the levels of RelA in infected cells." (PMID 26933955, 2016). "Overall this data implies that the TLR-activated host factors NFκB (RelA), SP1, RXR and members of the IRF family play a central role in activating the enhancer in infection and that these factors may form a functional network." (PMID 25856589, 2015). "Similarly, expression levels of the NF-κB transcription factors, NF-κB1/p50 and RelA/p65, were recovered in c-KIT-silenced cells in response to Y. enterocolitica WA infection." (PMID 24206648, 2013). "During early infection, γHV68 hijacks MAVS and IKKβ to induce the site-specific phosphorylation of RelA, a crucial subunit of the transcriptionally active NFκB dimer, which primes RelA for the proteasome-mediated degradation." (PMID 22110409, 2011).
infection (continued). "The fact that cyclohexamide treatment, at 30 min post-infection, did not abolish γHV68-induced RelA degradation implies that a structural component(s) of the incoming virion is capable of accelerating RelA turnover." (PMID 22110409, 2011). "Since CMV infection induces the canonical (NF-κB1/RelA; NF-κB1/RelB) and noncanonical (NF-κB2/RelB) NF-κB pathways, we postulated that mCMV infection of E11 MANs would induce changes in NF-κB protein expression and localization." (PMID 18371224, 2008). "These initial findings indicated that IE72 and IE86 inhibit the phosphorylation of RelA/p65 at Ser536 and that acute infection with HCMV does not induce RelA/p65 phosphorylation at Ser536 (unlike the case observed in the background of infection with other microbes)." (PMID 35269913, 2022). "The essence of SpoT but not RelA for S. Typhimurium dormancy could suggest that either or both the (p)ppGpp hydrolysis and synthase function is required, or relA is not expressed during the course of infection." (PMID 33930101, 2021). "Previous studies for screening of three deletion mutants in cattle and goats revealed one mutant, with a deletion in relA (ΔMap/relA), could not establish a persistent infection." (PMID 29941017, 2018). "The ability of shp65/RelA-expressing HeLa cells to sustain an efficient MeV replication was not due to a better infection of these cells since we observed an equivalent level of expression of the MeV cell surface receptor CD46 on shp65/RelA- and shControl-expressing cells." (PMID 28531150, 2017). "Given that ΔUL26 infection fails to block the expression of cytokine signaling genes, we assessed whether the inactivation of STAT1 or RELA, endpoint transcription factors associated with activated STAT and NFκB signaling, respectively, would rescue ΔUL26 replication defects." (PMID 38768227, 2024). "Phosphorylation of the RelA/p65 domain at the serine 536 (Ser536) residue significantly impacts the stability and protein interactions of NF-κB via a conformational change, and it enhances NF-κB transactivation in response to infection with microbes, but this is not known in HCMV infection." (PMID 35269913, 2022). "In contrast, infection neither affected expression of key activators of the TLR pathway (IRAK1, MYD88, and RELA) nor RELB, a key element pivotal for DC differentiation, maturation, and MHC Class I-restricted presentation." (PMID 32582184, 2020).
bacterial infection (7 papers, 2004 to 2023). "To gain insight into the mechanism by which the PipA family of effectors targets RelA, we examined the localization of PipA, GtgA, and GogA both, after transient transfection or bacterial infection." (PMID 26933955, 2016). "When TNFR1 is mutated together with the mammalian NF-κB gene RelA, TNFR1/RelA-deficient mutant mice exhibit severe susceptibility to bacterial infection, hematopoietic defects and significant reductions in neutrophil recruitment to sites of injury and injected bacteria." (PMID 25674081, 2015). "Although, a defect in the colonic patches in Nfkb2−/− mice could impair IL-22 mediated protective responses, our cell-intrinsic crosstalk model explained that the reported epithelial requirement of LTβR is in sustaining RelA NF-κB response during bacterial infection." (PMID 25905673, 2015). "Moreover, RelA silencing did not change the kinetic of RIPosome formation upon bacterial infection as indicated by immunoblot and fluorescence microscopy." (PMID 31350258, 2019).
inflammation (7 papers, 2017 to 2025). Aberrant reaction of the microcirculation characterized by movement of fluid and leukocytes from the blood into extravascular tissues. "Furthermore, the ability of Parabacteroides to improve COPD-associated lung inflammation through the lung-gut axis may be related to its regulation of the key target genes ReLA and HDAC1, thereby reducing the production of NETs in the lungs." (PMID 39629210, 2024). "Taken together, these results show that RELA is deacetylated in fibrotic and acute liver inflammation in vivo, and in LPS-stimulated primary hepatocytes in vitro." (PMID 41322258, 2025). "In vascular smooth muscle cells, induced by vasoconstrictor angiotensin II, RHOA mediates phospho-Ser536 nuclear factor κB/RelA subunit exchange on the IL-6 promoter, thereby mediates IL-6 expression and vascular inflammation." (PMID 37781036, 2023). "To further determine the role of RELA deacetylation mediated by SIRT7 in largemouth bass, we established a LPS-induced fish model with acute liver inflammation and isolated primary hepatocytes followed by LPS stimulation." (PMID 41322258, 2025).
cardiovascular disease (6 papers, 2014 to 2023). "According to previous reports, RELB, HAND1, and RELA are critical transcriptional factors in cardiovascular disease, and RELB and RELA have been confirmed to be related to AS progression." (PMID 37325477, 2023). "Resveratrol activates Sirtuin-1 (Sirt1) inhibiting RELA acetylation and promoting inhibitor protein-κBα (IkBα) degradation in the immune response and cardiovascular disease." (PMID 35166167, 2022). "RELA is a crucial regulatory factor of NF-kappaB, which is closely related to cardiovascular disease and involved in various inflammatory responses." (PMID 34567206, 2021). "We constructed an mRNA–miRNA–lincRNA ceRNA interaction network centered on miR-22-3p and used the starBase v2.0 and miRWalk databases to predict eight related transcription factors associated with cardiovascular disease, namely, CTCF, JUN, JUND, NFATC1, NFE2L2, RAD21, RELA, and TAL1." (PMID 36105099, 2022). "Wang and so forth revealed that SIRT1 inhibits transcription of RelA/p65 subunit by deacetylation of NF-κB and reduces the generation of oxygen free radicals so as to inhibit the main pathological factors which promote atherosclerosis and cardiovascular disease." (PMID 25114706, 2014).
neurodegenerative disease (5 papers, 2013 to 2022). A disorder of the central nervous system characterized by gradual and progressive loss of neural tissue and neurologic function. "Here, we discuss the effect of unbalanced activation of RelA and c-Rel during aging and propose novel challenges for the development of therapeutic strategies in neurodegenerative diseases." (PMID 26042083, 2015). "Nevertheless, the homodimers RelA/RelA and p50/p50 are also related to neuronal protection, since overexpression of RelA/RelA decreases apoptosis in primary cortical neurons and nfκB1 null mice exhibit increased cell death under conditions that mimic neurodegenerative diseases." (PMID 23708099, 2013).
adenocarcinoma (4 papers, 2005 to 2022). A common cancer characterized by the presence of malignant glandular cells. "An adenocarcinoma with strong cytoplasmic staining for p65/RELA with moderate staining for phospho-Akt and cIAP-2 is also shown." (PMID 16332260, 2005). "Forty-two out of 82 adenocarcinomas (51.2%) showed cytoplasmic overexpression in neoplastic ducts, the remaining cases were RelA-negative." (PMID 17622249, 2007).
hematologic malignancies (2 papers, 2022). "Among multiple proteins involved in cell survival decisions, one such protein is RelA/p65, the most abundant component of the canonical NF-κB pathway, which plays an important role in drug resistance (acquired in particular) involving both solid tumor and hematologic malignancies." (PMID 35574302, 2022).
liver (2 papers, 2023 to 2025). "RELA K119 deacetylation enhances RELA transcriptional activity by increasing its DNA-binding activity, and facilitates nuclear translocation of RELA, resulting in the overwhelming release of proinflammatory factors, and subsequently enhancing liver inflammation and fibrosis." (PMID 41322258, 2025).